TMX1 (thioredoxin related transmembrane protein 1)
Description:
Thioredoxin domain-containing protein that participates in various redox reactions through the reversible oxidation of its active center dithiol to a disulfide and catalyze dithiol-disulfide exchange reactions. Acts as a key inhibitor of the alternative triglyceride biosynthesis pathway by inhibiting the activity of TMEM68/DIESL at the endoplasmic reticulum, thereby restricting accumulation of triacylglycerol. The alternative triglyceride biosynthesis pathway mediates formation of triacylglycerol from diacylglycerol and membrane phospholipids. Acts as a protein disulfide isomerase by catalyzing formation or reduction of disulfide bonds. Specifically mediates formation of disulfide bonds of transmembrane proteins at the endoplasmic reticulum membrane. Involved in endoplasmic reticulum-associated degradation (ERAD) via its protein disulfide isomerase activity by acting on folding-defective polypeptides at the endoplasmic reticulum membrane. Acts as a negative regulator of platelet aggregation following secretion in the extracellular space. Acts as a regulator of endoplasmic reticulum-mitochondria contact sites via its ability to regulate redox signals. Regulates endoplasmic reticulum-mitochondria Ca(2+) flux.
Synonyms: TMX; TXNDC; TXNDC1; PDIA11
Tractability: Antibody: UniProt places it where antibodies can reach, with high confidence; UniProt predicts a signal peptide or a membrane-spanning region; its Gene Ontology location is reachable by antibodies, with medium confidence. PROTAC: ubiquitination databases record sites on it; its protein half-life has been measured.
Gene: Protein-coding gene on chromosome 14 (51,240,162 to 51,257,655, forward strand). Ensembl gene ENSG00000139921.
Subcellular location: Endoplasmic reticulum membrane; Mitochondrion membrane; Secreted
Subcellular location (Human Protein Atlas): Endoplasmic reticulum; Nucleoli
Gene Ontology:
Molecular function: disulfide oxidoreductase activity; enzyme inhibitor activity; protein binding; protein disulfide isomerase activity; protein-disulfide reductase activity
Biological process: negative regulation of platelet aggregation; negative regulation of triglyceride biosynthetic process; positive regulation of ERAD pathway; regulation of calcium ion transport; response to endoplasmic reticulum stress
Cellular component: endoplasmic reticulum; endoplasmic reticulum membrane; mitochondria-associated endoplasmic reticulum membrane contact site; mitochondrial membrane; nucleolus; endomembrane system; extracellular region
Genetic constraint (gnomAD): Loss-of-function variants: 27 observed, 36.86 expected, observed/expected ratio (o/e) 0.73, 90% interval 0.54 to 1.01. The upper end of that interval is the gene's LOEUF score, 1.01, which puts it in group 4 of 6, group 1 being the genes least tolerant of losing a copy. Missense variants: 338 observed, 344.11 expected, observed/expected ratio (o/e) 0.98, 90% interval 0.9 to 1.08. Synonymous variants: 131 observed, 121.27 expected, observed/expected ratio (o/e) 1.08, 90% interval 0.94 to 1.25.
Homologues: Orthologues: chimpanzee TMX1 (99% identical), dog TMX1 (92% identical), pig TMX1 (90% identical), rabbit TMX1 (87% identical), guinea pig TMX1 (82% identical), macaque TMX1 (81% identical), rat Tmx1 (79% identical), mouse Tmx1 (77% identical), tropical clawed frog tmx1 (58% identical), zebrafish tmx1 (52% identical), Caenorhabditis elegans pdi-2 (19% identical), Caenorhabditis elegans pdi-1 (17% identical), and 6 more. Paralogues in human: TMX4 (40% identical), TXNDC11 (22% identical), PDIA2 (21% identical), P4HB (21% identical), PDIA4 (19% identical), PDIA3 (18% identical), PDIA6 (18% identical), PDILT (16% identical), TMX3 (16% identical), PDIA5 (14% identical), TXNDC5 (13% identical), ERP44 (12% identical), and 1 more.
Diseases named in the same sentence as TMX1 in open-access papers:
TMX1 is named in the same sentence as 11 diseases in open-access papers, as found by Europe PMC text mining. Sharing a sentence is not in itself a finding about the gene and the disease. The quoted sentences say what the papers report.
breast carcinoma (1 paper, 2012). "In general, more aggressive breast cancers (MDA-MB-231, SUM159PT, BCCL2, BCCL3) had lower levels of TMX1 and SOD1 relative to the luminal MCF-7 cells, and showed up-regulated expression of TMX3, Foxo1, GSS and SOD2." (PMID 22479642, 2012).
hepatocellular carcinoma (1 paper, 2017). A malignant tumor that arises from hepatocytes. "Furthermore, this BFA‐induced conversion of TMX1 to the oxidized form was also observed in human hepatocellular carcinoma cell line HepG2 cells." (PMID 29123984, 2017).
liver cancer (1 paper, 2023). An epithelial or non-epithelial malignant neoplasm that arises from the liver. "In addition, TMX1, TMX2, and TMX3 are highly expressed in liver cancer cell lines, while TMX4 expressed is upregulated in melanoma cell lines." (PMID 38147024, 2023).
ovarian carcinoma (1 paper, 2024). A malignant neoplasm originating from the surface ovarian epithelium. "Recent research has revealed the predictive significance of TMX1 and SF3B4 in ovarian cancer, as well as their roles in proliferation and motility, respectively." (PMID 39309198, 2024).
pancreatic cancer (1 paper, 2025). "TRIM9 was found to be a protective factor for pancreatic cancer in both the bbj_a_140 and ebi-a-GCST90018673 datasets, and it exhibited colocalization with genes such as TMX1 and PYGL." (PMID 41050689, 2025).
tumor (16 papers, 2017 to 2025). "For example, TMX1 expression is associated with properties of tumor growth, and it has been proposed as a candidate antioncogene for breast cancer." (PMID 38147024, 2023). "Furthermore, while loss of TMX1 in these cancer cell lines accelerated tumor growth, TMX1 overexpression had the opposite effect." (PMID 28516062, 2017). "The TMX1 gene, located in the risk region on chromosome 14, has been reported to be widely expressed in normal human tissues, and has been suggested to act as a tumor suppressor." (PMID 29299148, 2017). "TMX1 can negatively regulate the function of SERCA2b, and tumor cells with low expression levels of TMX1 exhibit higher levels of Ca2+ in the ER." (PMID 33809551, 2021). "From a physiological point of view, TMX1 levels and TMX1-regulated calcium homeostasis impact on tumor growth and in vivo studies reveal a tumor-protective role for TMX1." (PMID 32878123, 2020). "TMX1, as a thiol-based tumor suppressor, may function by increasing mitochondrial ATP production and promoting the apoptotic process." (PMID 40977744, 2025). "In addition, TMX1, as a thiol-based tumor suppressor, can increase mitochondrial ATP production and apoptosis progression." (PMID 30602706, 2018). "TMX1, a redox-sensitive oxidoreductase that is enriched in the MAMs in a palmitoylation-dependent manner, was shown to regulate mitochondrial bioenergetics and in vivo tumor growth by controlling ER–mitochondrial Ca2+ signaling." (PMID 28516062, 2017). "Moreover, findings from our lab and others have shown that MAM proteins such as the oxidoreductase TMX1 indeed can determine the balance between tumor cell glycolysis and oxidative phosphorylation." (PMID 28603693, 2017). "Low levels of thioredoxin-related transmembrane protein 1 (TMX1) in cancer cells elevate ER Ca2+, faster cytosolic Ca2+ clearance, and reduced Ca2+ transfer to the mitochondria, reduce ER-mitochondria contact, shifts bioenergetics away from mitochondria, and speeds up tumor growth." (PMID 38534454, 2024). "TMX1 targets the MAM via its thioredoxin motif and palmitoylation, influencing ER-mitochondria contact, which in turn affects bioenergetic supply and accelerates tumor growth." (PMID 40977744, 2025). "After 16 weeks of 4-NQO treatment, Grhl2 WT mice exhibited gross tumor nodule formation on the tongue, while Grhl2 KO mice (Tmx1) displayed complete absence of tumor nodule formation." (PMID 29735981, 2018).
cancer (11 papers, 2017 to 2025). A tumor composed of atypical neoplastic, often pleomorphic cells that invade other tissues. "As a consequence, loss of TMX1 in HeLa and A375P, a malignant melanoma cell line, increased ER Ca2+ retention and reduced ER–mitochondrial Ca2+ transfer." (PMID 28516062, 2017). "Additional work is also needed for the dissection of the molecular dynamics behind TMX1 modulation of SERCA2b function: these data will be also instrumental to determine if TMX1 could be exploited as both diagnostic and therapeutic target for the treatment of select cancers." (PMID 32878123, 2020). "Reduced levels of TMX1 in cancer cells lead to increased ER Ca2+ levels, and a concomitant decrease in cytosolic and mitochondrial Ca2+ levels resulting in reduced mitochondrial respiration." (PMID 32039198, 2019). "Among the MAM proteins that regulate ER-mitochondria Ca2+ flux and affect cancer cells, are the redox-sensitive oxidoreductase thioredoxin related transmembrane protein 1 (TMX1) and protein tyrosine phosphatase-interacting protein 51 (PTPIP51)." (PMID 32039198, 2019). "Accordingly, cancer cells displaying lower levels of TMX1 show an increased ER Ca2+ content and an accelerated cytosolic Ca2+ clearance, along with a reduced ability of the ER to direct Ca2+ toward mitochondria." (PMID 28868254, 2017). "Compared with healthy tissues, TMX1 showed a significant up-regulation in 10 cancer types." (PMID 38147024, 2023). "In this context, cells expressing low levels of TMX1 display a reduced mitochondrial metabolism, which confers resistance to the effect of mitochondrial poisons that are currently used as treatment for many cancers." (PMID 32878123, 2020). "Under such conditions, cancer cells that have lost TMX1 expression might have a growth advantage over cancer cells with high TMX1 expression." (PMID 28516062, 2017). "Therefore, therapeutic strategies targeting TMX1 may further enhance cancer cell death through mitochondrial metabolic regulation." (PMID 40661148, 2025). "Cancer cells with low TMX1 levels show increased ER Ca2+ levels, accelerated cytosolic Ca2+ clearance, and reduced Ca2+ transfer to mitochondria, indicating that inhibition of TMX1 may reduce the susceptibility of the heart to I/R injury via reducing MAM contacts." (PMID 31842269, 2019). "Interestingly, human cancer cells with impaired expression of TMX1 levels, when xenografted in nude mice exhibited faster tumor growth, which was explained by a metabolic reprogramming and induction of a Warburg phenotype in these cancer cells." (PMID 28868254, 2017). "By estimating StromalScore and ImmuneScore in TME, we found that TMX1, TMX3, and TMX4 exhibited a positive correlation with StromalScore and StromalScore in most cancer types, while TMX2 expression was negatively correlated with StromalScore and ImmuneScore." (PMID 38147024, 2023). "Interestingly, it was shown that although cancer cells lacking TMX1 proliferate slower and display more spontaneous cell death, they are more resistant to mitochondrial stress inducers like rotenone and antimycin." (PMID 28516062, 2017).
TMX1 also shares sentences with these, for which no sentence is quoted: glioma (4 papers); brain cancer (1); hepatitis C (1); melanoma (1).